ENSG00000302876 (novel transcript, antisense to TGIF1)
Gene: Long non-coding RNA gene on chromosome 18 (3,424,236 to 3,452,380, reverse strand). Ensembl gene ENSG00000302876.
Gene Ontology:
Biological process: RNA processing
Cellular component: nucleolus